MMP9 (matrix metallopeptidase 9)
Diseases named in the same sentence as MMP9 in open-access papers (continued):
Sharing a sentence is not in itself a finding about the gene and the disease.
cancer (continued). "Metalloproteinases are broadly recognized as being involved in cancer cell invasion and migration; thus, we analyzed the effects of TFEB on metalloproteinases by detecting the expression level of MMP2 and MMP9." (PMID 33732651, 2021). "In TILs, MMP‐9 significantly degrades NKG2D and abrogates its ability in recognizing cancer cell antigens." (PMID 34486239, 2021). "This phenomenon is also documented in other types of cancer, as GPNMB promotes the invasion and proliferation of prostate cancer cell lines through the activation of MMP-2 and MMP-9, which can be reversed by GPNMB knockdown by siRNA transfection." (PMID 34054862, 2021). "Further, we revealed that preventing crosstalk between CAFs and cancer cells partially inhibits cancer stemness and gemcitabine resistance and decreases the expression of metastasis-related genes such as MMP2, MMP9, and Snail." (PMID 33782384, 2021). "These cytokines have been identified to be directly or indirectly responsible for cancer progression through remodeling of ECM by upregulating the expression of molecules such as MMP2, MMP3, MMP9, MMP10, MMP13, PLAU, ICAM1 and VCAM1." (PMID 34946170, 2021). "By gelatin zymography, we have shown that MB49 cancer cells secreted pro-forms of MMP-2 and MMP-9 in the culture medium when cultured in vitro." (PMID 34199232, 2021). "Further detailed molecular analyses indicated that cancer cell–platelet interaction induced the expression of EMT-related genes in GC cells, and MMP9 was the most notably changed gene in the microarray analyses." (PMID 33110200, 2021). "In the PDX model, most downregulated genes affected by OC-X treatments included MMP9, CXCL12, MMP13, and POSTN within the selected cancer stages." (PMID 34069906, 2021). "Other studies show that PGV-1 inhibits matrix metalloproteinase 9 (MMP9) expression and cancer cell migration on 4T1 cells, indicating that PGV-1 can also be developed as an inhibitor of TNBC metastasis." (PMID 34582664, 2021). "Matrix metalloproteinases, which belong to a large family of proteases, have been demonstrated to play vital roles in tissue remodeling and cancer progression and metastasis, of which MMP2 and MMP9 are the most important." (PMID 33573671, 2021). "However, upregulated expressions of MMP-2 and MMP-9, accompanied by downregulated TIMPs, were found in high-grade tumors, suggesting that interrupting the delicate balance between MMPs and TIMPs could affect tumor cell migration and cancer metastasis." (PMID 33535458, 2021). "When comparing expression patterns of both active and total MMP-9, active MMP-9 was presented almost only in cancer tissue and correlated with age, LNM, and ETE." (PMID 34684168, 2021). "In some cancer types, VEGF, AR, and HIF-1 cross talk have already been recognized, similar to AR/MMP9/VEGF cross-talk." (PMID 33920263, 2021). "Rh2 also diminished metastatic activities of pancreatic (Bxpc-3 at a dose of 45 μM) and lung (A549 at a dose of 60 and 100 μM) cancer cells via inhibition of MMP-2 and MMP-9." (PMID 33671187, 2021). "The prognostic role of MMP-2, MMP-9, and MMP-14 in UM was recognized in several studies due to their crucial role in promoting cancer cell motility and angiogenesis, ultimately leading to the development of metastases." (PMID 34195299, 2021). "IL-6 was previously reported to induce the expressions of COX-2 34, 35, MMP-9 36, Oct3/4 37, SOD2 38, 39 and CAT 39 in cancer cells." (PMID 33854627, 2021). "We revealed that miR-491-5p also directly targeted RABIF and downregulated RABIF-mediated TNBC cancer stemness, drug resistance, cell invasion, and pulmonary metastasis via matrix metalloproteinase (MMP)-2 and MMP-9 signaling." (PMID 34685504, 2021). "For instance, using a co-culture system of fibroblasts and cancer cells, changes in the gene expression involved in EMT have been proposed along with increase of cell growth and MMP-9." (PMID 33802621, 2021).
cancer (continued). "It inhibited the secretion of the cancer metastasis-relevant matrix metalloproteinases MMP-2 and MMP-9, and also the growth of Staphylococcus aureus biofilms by ca 87% when applied at concentrations as low as 0.5 μg/mL." (PMID 34677482, 2021). "Other known targets of miRNAs in cancers include MMP2, MMP9, MMP13, MMP14, and MMP16 and their substrates such as type I, II, and IV collagens." (PMID 33920915, 2021). "MMP9 is secreted by paracrine cancer cells with high STAT3 signal transduction, and STAT3 can regulate MMP9." (PMID 34876128, 2021). "Reportedly, HMGB1 can promote the invasion of NSCLC cells by activating PI3K/Akt and NF-κB pathways to produce MMP-9; in metastatic pancreatic ductal adenocarcinoma, HMGB1 promotes EMT and invasion of cancer cells by acting on RAGE/NF-κB axis." (PMID 33926347, 2021). "As two crucial members of the MMP family, MMP-2 and MMP-9 have also been found to participate in EMT and cancer metastasis." (PMID 34413913, 2021). "Matrix metalloproteinase, such as MMP9, was required in the EMT process of cancer cells via degrading the cellular adhesion." (PMID 34178646, 2021). "MMP9 promotes TGFβ1 induced EMT leading to increased migration and invasion capacity of thyroid, lung and esophageal squamous cancer cells." (PMID 33809973, 2021). "In previous studies, Fascin-1 is reported to regulate migration and invasion of cancer cells via upregulating matrix metalloproteinases (MMP) expression, such as MMP2 and MMP9." (PMID 34897283, 2021). "In colorectal cancer cell, sevoflurane inhibits cancer invasion and migration by downregulation of ERK (extracellular signal-regulated kinases) pathway and MMP-9 via miR-203 upregulation." (PMID 33750303, 2021). "These two cancer cells have known for the elevated MMP-2 and MMP-9 expressions, which is relevant to the aim of the present study." (PMID 34181339, 2021). "Genes such are GSTA4, GSTO2, KLK3, PGF were down-regulated and E2F2, MMP9, PIM2, VEGFC are up-regulated in all cancer nodules." (PMID 34209090, 2021). "It is documented that induction of MAPK/ERK or PI3K/Akt contributes to cancer cell invasion by regulating MMP-2 and/or MMP-9 40-42." (PMID 34149918, 2021). "The expression of MMP-2 and MMP-9 was significantly increased in patients with malignant tumors, more importantly, MMP-2 and MMP-9 are essential in in NSCLC invasion and metastasis." (PMID 34895234, 2021). "It has been shown that MMP-9 and MMP-2 released from CAFs can stimulate the potential of invasion and migration in carcinoma cells." (PMID 34680267, 2021). "Matrix metalloproteinase 2 (MMP2), matrix metalloproteinase 9 (MMP9), snail, and slug are closely related to the migration and invasion of a range of human cancer cells." (PMID 32503225, 2020). "We have compared protumorigenic phenotypes of rapidly metastatic murine cancer cell line LuM1 with a parental cancer cell line Colon26 (aka CT26) and shown that MMP3 and MMP9 were highly expressed in LuM1 cells." (PMID 32429403, 2020). "Among the differentially expressed genes, we found that several genes related to cancer progression (HMGA2, PLD2, MMP9, GLI1, GLI2, SLUG and MDR1) were expressed at a low level after knocking out APN." (PMID 32457292, 2020). "Invasive abilities of cancer cells are related to migration and many other factors, including expressions of MMP-2, MMP-9, Rac1, Rho A, and SOD2." (PMID 31772330, 2020). "Accumulating evidence has shown that cancer cells activate various types of MMPs, including MMP2, MMP7, MMP9, and MMP14, to facilitate migration to other organs." (PMID 32283687, 2020). "In suppressing metastasis of cancer cells, apigenin administration interferes with the PI3K/Akt/mTOR signaling pathway as well as the expression of MMP-9, as a factor involved in the progression and invasion of cancer cells." (PMID 33195038, 2020).
cancer (continued). "Evidence supporting our findings regarding mobilized cells against gravity are cancer cells that polymerize actin to form protrusions and activate their migration pathways as MMP-2, MMP-9, under microgravity environments." (PMID 33158020, 2020). "Our results suggest that matrine can block the cancer metastasis through the negative regulation of CXCR4 and MMP-9/2 and consequently it can be considered as a potential candidate for cancer therapy." (PMID 32630806, 2020). "CD147 been reported to enhance the invasive potential of cancer cells in part due to overexpression of MMP-2 and MMP-9 (Metalloproteinase 2 and 9)." (PMID 31973205, 2020). "Benztropine also reduced the activity of oncogenic signaling transducers and trans-activators for MMP9, including STAT3, NF-κB, and β-catenin, and the properties of cancer stem cells/cancer-initiating cells." (PMID 32102440, 2020). "It is worthy of note that in some cancer cell types, the microRNAs hampering MMP-9 expression are downregulated, which additionally increases MMP-9 protein levels and cellular invasion." (PMID 32630531, 2020). "This is the key step in the cancer cell invasion and metastasis, as a lot of flavonoids of MMP-2 and (or) MMP-9 have an inhibitory effect." (PMID 33265939, 2020). "Factors secreted by TAMs, such as TGF-β, VEGF, CCL8, COX-2, MMP9, and MMP2 also contribute to the metastatic properties of cancer cells." (PMID 33352665, 2020). "Transcriptional activation of MMP2 and MMP9 by TGF-β signaling is correlated with the migration and invasion of cancer cells." (PMID 33246423, 2020). "As a primary component of NETs, MMP-9 is mainly secreted by neutrophils and plays an important role in ECM remodeling and membrane protein cleavage, promoting cancer cell invasion, migration, metastasis, angiogenesis, inflammation, and proliferation." (PMID 33042821, 2020). "The transendothelial migration of EMT cancer cells is facilitated by both VEGF-promoted vascular permeability and the interaction between MMP-9 and neuronal-cadherin." (PMID 32630531, 2020). "To confirm that, here we performed a JNK or JAK2 inhibitor test by assessing the anti-cancer effects of pKAL on CD44, Oct 3/4, β-catenin, and MMP-9 as well as the STAT 3 activity of RT-R-MDA-MB-231 cells." (PMID 32326231, 2020). "The cancer metastasis is characterized by the depletion of E-cadherin and upregulation of Snail and metalloproteinases (MMP2 and MMP9)." (PMID 32365503, 2020). "MMP-2 and MMP-9 were measured by ELISA to examine the inhibitory effects of TAO on extracellular matrix degradation and presumably cancer metastasis." (PMID 33086573, 2020). "In turn, cancer cell-derived signals triggered the expression of metalloproteinases (MMPs) including MMP2, MMP9, and MMP12 in SCs, promoting SCs to dissolve matrix." (PMID 32064233, 2020). "Overactivated NF-κB signaling upregulates MMP9 and MMP2 expression to facilitate migration and invasion of cancer cells." (PMID 32637415, 2020). "Matrix metalloproteinases (MMP) family such as MMP-9 and MMP-2 can play an important role in cancer proliferation, invasion, and metastasis." (PMID 33027960, 2020). "Marimastat inhibits MMP-2, MMP-9, MMP-1, and other MMPs and, it has been reported to inhibit cancer cell migration 3D in vitro at a 30 μM concentration and to inhibit fibroblast mediated collagen hydrogel contraction at a 10 μM concentration." (PMID 32384738, 2020). "MMP-9, MMP-14, ADAM-12 and ADAM-17 are some of the MPs that were found to have a significant role in several types of cancer." (PMID 32466129, 2020). "In live cancer, TPX2 inhibited the expression of MMP2 and MMP9 to suppress cell invasion and metastasis." (PMID 33098235, 2020). "Previous studies showed that a sublethal RT dose induces the up-regulation of matrix metalloproteinase 9 (MMP-9), which promotes cancer cell survival and metastasis." (PMID 32143669, 2020).
cancer (continued). "In ER-negative breast cancer, CXCL1 enhances cancer cell migration and invasion through an ERK/MMP2/MMP9 signal pathway." (PMID 33256011, 2020). "AIM suppressed TNF-α effects on the NF-κB-regulated proteins involved in cancer cell proliferation (COX-2, and C-myc), invasion, and angiogenesis (MMP-2 and MMP9, ICAM-1 and VEGF)." (PMID 32455624, 2020). "Key cancer-related pathways and proteins that these genes can regulate include the AKT/GSK-3β/SNAIL pathway, MMP-9, CD44 and STMN1 which are involved in EMT and metastasis." (PMID 33374923, 2020). "Protein–protein interaction analysis of common DEGs in L. brandtii showed that the most significant core genes were CXCL1, MMP9, JUN, ANXA2, and F5, which regulate immune response and cancer progression." (PMID 32256671, 2020). "Biologically, macrophages mediate adhesion, facilitate the EMT process in cancer cells and promote distant metastasis spread via secreting various soluble factors, such as IL-1β, IL-8, TNF-α, TGF-β, MMP-9." (PMID 33081056, 2020). "In our study, we analyzed the Cancer Cell Line Encyclopedia (CCLE), The Cancer Genome Atlas (TCGA), and the Genomics of Drug Sensitivity in Cancer (GDSC) database, to select six genes (FBN1, FN1, HGF, MMP9, THBS1, and VCAN) as target genes." (PMID 33014013, 2020). "The protein levels of MMP12, MMP9 and TIMP3 are increased in cancer cells compared to controls after 48 h culture." (PMID 32171282, 2020). "Many factors, such as TGF-β, activating protein-1 (AP-1) and EGF, interact with the promoter of MMP9 and MMP2 to induce the expression of MMP9 and MMP2 in cancer cells." (PMID 32637415, 2020). "When MMP-9 is translated and activated, enzymatic activity digests type IV collagen in the extracellular matrix (ECM), which favors cancer cell metastasis to nearby tissues, and eventually invasion to other organs by disrupting local cell basement membranes." (PMID 32328465, 2020). "In various types of cancer tissues, IL8 participates in degradation of the extracellular matrix by promoting the expression of MMP-2 and MMP-9 in cancer cells." (PMID 33046030, 2020). "Following NF-κB inhibition, the cancer-related genes like Bcl-2, Bcl-xL, cyclin D1, IL-6, COX-2 and MMP9 are subsequently downregulated." (PMID 32131560, 2020). "The roles of MMP-2, MMP-9, ICAM-1, and VEGF are well known in the invasion and angiogenesis of cancer." (PMID 32455624, 2020). "Production and release of pro-MMP-9, which is activated to functional MMP-9, has been shown to lead to degradation of ECM proteins enhancing cancer progression, similar to our study." (PMID 31919471, 2020). "In cancer cells that exhibit LCN2 overexpression, LCN2’s modulation of MMP-9 seems to be crucial for the invasion of malignant cells through the basement membrane; this modulation occurs through three different mechanisms." (PMID 32575507, 2020). "In conclusion, taken together, the combination of Hst and Dox inhibited cancer cell’s growth and metastasis through cell cycle arrest, apoptosis, reduce cell migration, decrease HER2, Rac1, and MMP9 expression." (PMID 32458631, 2020). "A collation of 73 TEC marker genes from five studies showed that at most, only two cancer types shared one of these five genes (EGFL6, HEYL, MMP9, SPARC, PLXDC1), and the rest were expressed uniquely in only one cancer." (PMID 32375250, 2020). "As reported, MMP-2 and MMP-9 can regulate the ERK signaling pathway, thereby promoting migration and invasion of cancer cells." (PMID 32670867, 2020). "Expression of genes that played a pivotal role in cancer cell migration, including VEGFA, PLAU, MMP2, MMP9, and MMP14, were reduced in dose-dependent manner of stigmasterol in both cell lines." (PMID 32481565, 2020). "MMP-9 is the most studied and important MMP family member in cancer tissue remodeling via degradation of denatured collagens (gelatins) of ECM, in particular collagen types V, VII, IX, as well as elastin and fibrin among others." (PMID 32944046, 2020).
cancer (continued). "The NOB suppresses the motility and invasion of cancer cells via the downregulation of MMP-2 and MMP-9." (PMID 32380783, 2020). "Matrix metalloproteinases (MMPs) play significant roles in cancer diseases, with MMP-2 and MMP-9 being important types among the various MMPs." (PMID 32967141, 2020). "MMP‐2 and MMP‐9, two important ECM‐degrading enzymes, participate in cancer cell migration and invasion." (PMID 32180962, 2020). "In line with this, two studies to date demonstrate that enhanced expression of LDHC induces epithelial-to-mesenchymal transition, matrix metalloproteinase-9 (MMP9) expression and promotes cancer cell migration and invasion." (PMID 31932876, 2020). "Upon examination of VE-cadherin, ephrin A2, VEGFR2, laminin 5γ2, MMP1, MMP2, MMP9 and MMP14 by the human cancer cells, we made the surprise finding that of the genes investigated, VE-cadherin (CDH5) was the most highly expressed." (PMID 32246008, 2020). "AIM suppressed the TNF-α effects on the NF-κB-regulated proteins involved in cancer cell proliferation (COX-2, C-myc), invasion, and angiogenesis (MMP-2, MMP9, ICAM-1, and VEGF)." (PMID 32455624, 2020). "In contrast, cell proliferation gene (BRAF), ECM-degrading gene (MMP9), cell cycle regulating and WNT signalling pathway regulator (APC) were expressed higher in the cancers of early pathological stages." (PMID 33092235, 2020). "Among the 24 members of the MMP family, previous researches have focused on the tumourigenic role of MMP9 and MMP2 for many malignant carcinomas." (PMID 31937294, 2020). "Emodin, an active anthraquinone present in A. vera, inhibits cancer growth by suppressing the expression of MMP7, MMP9, VEGF, EMT, N-cadherin, β-catenin, and Snail." (PMID 30871059, 2019). "MMP-9 cleaves and releases gelatin and type IV collagen, which compromises the ECM integrity and allows cancer stem cells to invade the ECM by binding to released ECM proteins." (PMID 31533268, 2019). "In particular, IL-6 exerts a pro-metastatic effect in gastric SGC7901 cancer cells that show high levels of both MMP-2 and MMP-9 in conditioned medium." (PMID 31817563, 2019). "Invadopodia facilitate the ECM degradation in a variety of cancers through the regulation of various MMPs, primarily MMP-14 (also known as MT1-MMP), MMP-2 and MMP-9." (PMID 30927923, 2019). "MMP-9 is an irreplaceable player in the degradation of ECM whose abnormal expression disequilibrates ECM and contributes to cancer cell metastasis." (PMID 31783821, 2019). "For example, they are inhibited by gemcitabine (RRM2), marimastat (MMP9 and MMP11) for treating several cancers." (PMID 30729033, 2019). "Based on the results, MMP2, MMP9 and MMP14 expression levels were also reduced in cells treated with ampelopsin E. Production of MMPs correlates with the ability of cancer cells to perform EMT." (PMID 31323836, 2019). "Markedly more cases of malignant tumours were MMP‐9 (85.3%, 29/34)‐ and TGF‐β (79.4%, 27/34)‐positive; among them, 24 cases were both MMP‐9‐ and TGF‐β‐positive." (PMID 31264317, 2019). "In the process of cancer metastasis, MT1-MMP, MMP-9, uPAR, ICAM-1, and Cox-2 are responsible for cell migration, invasion, and adhesion." (PMID 31766230, 2019). "We also observed the up-regulation of TIM2 expression and down-regulation of MMP2 and MMP9 levels in EEL groups, which further proved the inhibiting ability of EEL on cancer metastasis." (PMID 31572063, 2019). "As MMPs are important in regulating cancer cell invasion and migration, we further examined the protein levels of MMP-2 and MMP-9 in SACC-83 and SACC-LM cells." (PMID 31762692, 2019). "The overexpression of many MMP family members, such as MMP2, MMP9 and MMP11 has been found to be involved in cancer progression 27-29." (PMID 31595150, 2019). "MMP9 and MMP2 are involved in the induction of the angiogenic switch, while an MMP9/VEGF axis controls cancer cell intravasation." (PMID 31737559, 2019).